VHL (von Hippel-Lindau tumor suppressor)
Diseases named in the same sentence as VHL in open-access papers (continued):
Sharing a sentence is not in itself a finding about the gene and the disease.
renal cell carcinoma (continued). "In conclusion, our findings elucidate a novel connection between hypoxia-induced repression of DNA repair and VHL loss in renal cell carcinoma." (PMID 29435132, 2018). "As renal cell carcinoma belongs to the most frequent cancers in the human population and simulates permanent hypoxic conditions due to VHL mutation, we were interested in the effect of LCMV strain MX infection on RCC4 cells." (PMID 29560117, 2018). "Von Hippel-Lindau (VHL) disease, caused by germline mutations in the VHL gene, is characterized by metachronously occurring tumors including pheochromocytoma, renal cell carcinoma (RCC), and hemangioblastoma." (PMID 30105105, 2018). "The remaining VHL mutation carrier demonstrated a family history of pheochromocytoma and renal cell carcinoma consistent with VHL syndrome." (PMID 30455982, 2018). "Given the crucial need for better treatment options in RCC, we believe that our findings support the investigation of PARP inhibitors in VHL-deficient human renal cell carcinoma." (PMID 29435132, 2018). "Four genes (BRCA2, CDK12, MLL2, and VHL) were differentially mutated (p-value < 0.05) between renal cell carcinoma patients and sarcoma patients; however, these differences were not significant when correcting for multiple comparisons (FDR q-values >0.5)." (PMID 29383146, 2017). "Here, we investigated its growth inhibitory properties on a panel of immortalized and patient derived renal cell carcinoma (RCC) cell lines which were either deficient in the tumour suppressor von Hippel-Lindau (VHL) protein or possessed a functional copy." (PMID 28582447, 2017). "In von Hippel Lindau (VHL)-deficient renal cell carcinoma (RCC), NOX4 also promotes renal tumorigenesis in a similar signal pathway via nuclear accumulation of HIF-2α, not HIF-1α." (PMID 28594389, 2017). "HIF-1α is often highly active in renal cell carcinoma due to mutations in VHL and subsequently accumulation of HIF-1α." (PMID 27906674, 2017). "We selected the F76del mutant VHL to address this issue because this mutation has been associated with distinct types of cancer such as renal cell carcinomas, PCCs and PGLs." (PMID 28036268, 2017). "Recent evidence revealed that cystine deprivation triggers RIP1/RIP3/MLKL-mediated necrosis in VHL-deficient renal cell carcinomas." (PMID 29383104, 2017). "Mutations of the Von Hippel-Lindau (VHL) tumor suppressor result in multiple benign and metastatic tumors, including renal cell cancer." (PMID 28361305, 2017). "A recent study showed that loss of tumour suppressor von hippel-lindau tumor suppressor (VHL) renders renal cell carcinomas sensitive to glutamine deprivation through hypoxia induced factor (HIF)-induced metabolic reprogramming." (PMID 27321283, 2016). "We then studied the tissue specificity of TGX221 and found that only renal cell carcinoma harbours VHL and/or SETD2 mutations in GDSC database and TGX221 exhibited sensitivity for RCC cells with such mutations." (PMID 25853938, 2015). "The upregulation of HIF in cells deficient in VHL is critically important in the tumorigenesis of renal cell carcinoma." (PMID 25373733, 2014). "Genomic analysis of multi-focal renal cell carcinomas from an individual with a germline VHL mutation offers a unique opportunity to study tumor evolution." (PMID 25159823, 2014). "For example, renal cell carcinoma (RCC) is almost entirely dependent on loss of VHL and induced hypoxic signaling involving VEGFR." (PMID 25594051, 2014). "The stability of Jade-1 is dependent on the presence of a functional von Hippel-Lindau (VHL) protein, downregulation of Jade-1by VHL mutations is thought to be responsible for the hyperactivation of the Wnt pathway in renal cell carcinoma." (PMID 24594309, 2014). "We have previously discovered Activin B as a target gene of HIF that is upregulated in renal cell carcinomas as a consequence of VHL mutation." (PMID 25343250, 2014).
renal cell carcinoma (continued). "We describe the earliest onset renal cell carcinoma in VHL disease reported so far in a 15-year-old boy with a nonsense VHL mutation." (PMID 23298237, 2013). "Investigation of rare familial forms of renal cell carcinoma (RCC) has led to the identification of genes such as VHL and MET that are also implicated in the pathogenesis of sporadic RCC." (PMID 24000165, 2013). "Mutations of the von Hippel-Lindau (VHL) tumor suppressor gene occur in the majority of sporadic renal-cell carcinomas (RCC)." (PMID 24195061, 2013). "The occurrence of RCC in a fifteen-years old boy with a truncating germline VHL mutation highlights that renal cell carcinoma can be detected in patients with nonsense VHL mutations younger than sixteen years of age." (PMID 23298237, 2013). "Type 2a is associated with a lower incidence of renal cell cancer, whereas VHL type 2b is associated with a high incidence of pheochromocytoma and hemangioblastoma." (PMID 23781388, 2013). "These included two isoforms of a fusion involving the genes BRK1 and VHL, whose co-deletion has previously been associated with the prevalence and severity of renal-cell carcinoma." (PMID 22761941, 2012). "HIF-2α is stabilized in von Hippel-Lindau (VHL)-deficient renal cell carcinoma through mechanisms that require ongoing mRNA translation." (PMID 23202921, 2012). "In the PTEN and VHL-deficient renal cell carcinoma line 786-O, RAD001 and BEZ235 strongly synergized in vitro and reduced cell viability with excess inhibition over Loewe additivity when 2.5–67 nM BEZ235 were combined with RAD001." (PMID 23155392, 2012). "Associated focal lesions (e.g., renal cell carcinoma) are caused by inactivation or silencing of the remaining wild-type VHL allele." (PMID 23202921, 2012). "Hypoxia-inducible factor (HIF) is an attractive therapeutic target for renal cell carcinoma (RCC) as its high expression due to the loss of von Hippel-Lindau (VHL) promotes RCC progression." (PMID 22295124, 2012). "Clinical and functional properties of novel VHL mutation (X214L) consistent with Type 2A phenotype and low risk of renal cell carcinoma." (PMID 20560986, 2011). "Type 1 VHL mutations are mostly deletions and truncation mutations that drastically alter pVHL and phenotypically manifest in a low occurrence of pheochromocytoma and high frequency of renal cell carcinoma." (PMID 19602254, 2009). "To test this possibility, we took advantage of a VHL-deficient human renal cell carcinoma cell line RCC4." (PMID 19223896, 2009). "We investigated the association between exposure to trichloroethylene (TCE) and mutations in the von Hippel-Lindau (VHL) gene and the subsequent risk for renal cell carcinoma (RCC)." (PMID 17997830, 2007). "Type 2 VHL has been further categorized into subtypes: type 2A (associated with a lower risk of renal cell carcinoma), type 2B (associated with a higher risk of renal cell carcinoma), and type 2C (associated with isolated pheochromocytoma)." (PMID 41179499, 2025). "VHL pathogenic variants contribute to 0.3–3% of renal cell cancer (RCC) incidence." (PMID 38390862, 2024). "Molecular biology methods can detect kidney cancer-related markers in urine or blood, such as DNA microsatellite alterations, VHL gene mutations or hypermethylation, renal cell carcinoma-specific proteins such as CA-9 expression, and upregulation of angiogenic factors such as VEGF expression." (PMID 37138262, 2023). "Additionally, p22phox, NOX1, and NOX2 induce HIF-2α transcription in VHL-deficient renal cell carcinoma." (PMID 38069210, 2023). "SETD2 and VHL are both commonly mutated genes in renal cell cancer." (PMID 37933774, 2023). "Additionally, VHL mutations indicate a diagnosis of SCA or a metastasis from a renal cell carcinoma, whereas CTNNB1 mutations a diagnosis of SPN." (PMID 35053560, 2022). "VHL inactivation, either by mutation or 3p deletion, was reported in 2 renal cell carcinomas." (PMID 33947144, 2021).
renal cell carcinoma (continued). "We speculate that the loss of VHL observed in renal cell cancer implies a constitutive response strategy due to rapid fluctuations in oxygenation early in its development." (PMID 33707510, 2021). "Interestingly, among the cancer types in pan-cancer cohort, bladder cancer ranks second after renal cell carcinoma in terms of VHL’s mutation frequency." (PMID 33319839, 2020). "We next asked if this trend could also be observed in renal cell carcinoma, a malignancy which frequently harbors VHL mutations leading to constitutive activation of HIF-1α." (PMID 31819034, 2019). "Furthermore, VHL loss of function mutations have been extensively investigated revealing that expression of VHL can be blocked by promoter hypermethylation in renal cell carcinoma and multiple myeloma." (PMID 30761299, 2019). "Furthermore, pathway enrichment analysis of the Low iAs/Low TCE differentially expressed genes identified the same pathways previously reported for the VHL P81S mutation from renal cell carcinomas in people exposed to industrial levels of TCE." (PMID 30898898, 2019). "The changes indicated a kidney cells manifested a tumor promotion state only from the combined exposure that was similar to gene expression changes elicited in an embryonic stem cell assay for the renal cell carcinoma mutation, VHL P81S, observed in patients exposed to TCE in an industrial setting." (PMID 30898898, 2019). "Renal tubular disease did occur both in all treatment groups, and a unique gene expression signature similar to that elicited by expressing a TCE-associated VHL mutation from renal cell carcinomas was observed specifically in the iAs and TCE combined treatment group." (PMID 30898898, 2019). "Moreover VHL-associated tumors such as renal cell carcinomas were described to be causative for elevated Hb or EPO levels." (PMID 30214643, 2018). "Interestingly, hereditary heterozygous mutations in another TCA cycle enzyme, fumarate hydratase (FH), also lead to the development of renal cell carcinomas following the loss of heterozygosity, similarly to VHL or SDH mutations." (PMID 29772792, 2018). "Interestingly, many of these studies are conducted against renal cell carcinomas where constitutive HIF-2α activation is frequently observed due to VHL mutations and CD70 is highly expressed." (PMID 29721188, 2018). "Together, our data elucidate a novel connection between VHL-deficient renal carcinoma and hypoxia-induced down-regulation of DNA repair, and identify potential opportunities for targeting DNA repair defects in human renal cell carcinoma." (PMID 29435132, 2018). "We further present evidence that profiling of clinical renal cell cancer tissues as expected shows high levels of hypoxia-induced genes suggesting extensive glycolysis, while also unambiguously revealing the presence of VHL mutations, all in line with known biology of these cancers." (PMID 28900252, 2017). "Whole exome sequencing of 4 renal cell carcinomas (RCC) occurring in a 32 yo man with Von Hippel Lindau syndrome led to identification of unique second hit mutations in VHL in each RCC, as well as 13–23 other somatic non-synonymous mutations throughout the genome." (PMID 27494029, 2016). "Renal clear cell carcinoma (RCC), arising in the proximal convoluted tubules of the kidney transport system, is the most common subtype of renal cell carcinomas (comprising about 88% of tumors) and is tightly associated with inactivating mutations of the VHL gene." (PMID 25298778, 2014). "In contrast, in patients with a negative family history of VHL-associated tumors, diagnosis of VHL can be made when such patients exhibit two or more CNS HBs or a single HB in association with a visceral tumor such as renal cell carcinoma, pheochromocytoma or pancreatic tumor." (PMID 28326249, 2014). "Moreover, the LC3B/ATG5-dependent autophagy was shown to be required for the development of VHL-deficient renal cell carcinomas in nude mice." (PMID 24763318, 2014).
renal cell carcinoma (continued). "In a similar vein, one may ask why somatic mutations in the VHL protein are primarily associated with renal cell cancer or why diminishing levels of testosterone prompt the kind of mutations that render the androgen receptor ligand-independent." (PMID 25265995, 2014). "Importantly, functional inactivation of VHL, including through germline mutations, has been well documented in highly vascularized tumors such as renal cell carcinomas, hemangiosarcomas, and pheochromocytomas." (PMID 22390300, 2012). "To determine whether the sirtinol-induced repression of HIF-1α protein is dependent on VHL, we used a VHL-deficient renal cell carcinoma, RCC4 VHL−/− and a VHL reconstituted, RCC4 VHL+/+ cell lines." (PMID 22479397, 2012). "We treated mice bearing 786-O tumor xenografts (human VHL deficient renal cell carcinoma) on the 4 described treatment regimens: 1) Conventional dose continuous, 2) high dose intermittent therapy, 3) conventional dose intermittent therapy, and 4) high dose continuous therapy." (PMID 22188900, 2011). "The potential role of HIF-2 upregulation of PTPRZ1 in renal cell carcinoma of particularly intriguing, as VHL is associated with renal cell carcinoma and there is evidence that HIF-2 is more important than HIF-1 in the renal cell carcinoma tumorigenesis in this setting." (PMID 20224786, 2010). "With the newly reported A3 and CC7 antibodies CA IX was shown to be expressed heterogeneously throughout the majority of the studied tumours, with exception of renal cell carcinomas in which all cancer cells express the antigen as a consequence of a mutated VHL gene." (PMID 19623173, 2009). "In renal cell carcinoma, radiogenomics is used to associate CT (Computed Tomography) and MRI features with specific genetic mutations, such as VHL (von Hippel–Lindau) mutations, which are common in RCC." (PMID 39852380, 2025). "In addition, genetic testing for mutation of the VHL tumor suppressor gene on chromosome 3p25–26 would have been useful in our case in view of the suspected renal cell carcinoma because of the correlation between the VHL gene alteration and the phenotype aggressiveness of the carcinoma." (PMID 39809053, 2025). "It accounts for ~75% of renal cell carcinoma (RCC) cases and is characterized by distinct genetic abnormalities, most notably the loss of function of the von Hippel-Lindau (VHL) tumor suppressor gene." (PMID 40461489, 2025). "For example, genetic mutations of von Hippel-Lindau (VHL) in renal cell carcinoma (RCC) lead to exceptionally high expression of VEGF through stabilization of hypoxia-inducible factor (HIF)-1α that transcriptionally controls VEGF mRNA expression." (PMID 38482486, 2024). "Risk factors and comorbidities might be associated to renal cell carcinoma, while a small fraction of 2–3% emerges from patients with predisposing cancer syndromes, typically associated to hereditary mutations in VHL, folliculin, fumarate hydratase or MET genes." (PMID 38512353, 2024). "Mutations of the von Hippel–Lindau (VHL) tumor suppressor gene occur frequently in clear cell renal cell carcinoma (RCC), the predominant histology of kidney cancer, and have been associated with its pathogenesis and progression." (PMID 39858553, 2024). "Additionally, a VHL-deficient renal cell carcinoma cell line (RCC4) was also tested." (PMID 39466364, 2024). "Renal cell carcinoma accounts for 80-90% of primary renal malignancies in adults, and based on histology and molecular subtypes, the most common type of RCC is clear cell carcinoma, which occurs frequently due to mutations in the VHL gene." (PMID 39697235, 2024). "Of the various RCC subtypes, clear cell renal cell carcinoma (ccRCC) is the most prevalent, characterized by the loss of the von Hippel–Lindau (VHL) tumor suppressor gene." (PMID 38928435, 2024). "VHL gene mutation is a common phenomenon in clear cell renal cell carcinoma, accounting for 80 to 90% of patients with RCC." (PMID 38072043, 2023).
renal cell carcinoma (continued). "Renal cell carcinoma (RCC) shows the loss of PCs connected with a downregulation of the von Hippel–Lindau (VHL) tumor suppressor gene." (PMID 37510333, 2023). "Ch’ng and colleagues investigated the cancer cell killing capability of NDV (AF2240) in renal cell carcinoma (RCC) containing wild-type or deficient VHL under hypoxic conditions." (PMID 36424577, 2022). "The VHL gene is a tumor suppressive gene found on chromosome 3p25-26, and the 25–45% of VHL syndrome patients who have this gene mutation can also present with renal cell carcinoma, pancreatic cysts, central nervous system and retinal hemangioblastoma, and pheochromocytoma." (PMID 36362756, 2022). "One genetic disturbance which is linked to the most common type of kidney cancer, renal cell carcinoma, RCC, occurs from mutations in the VHL gene." (PMID 35740352, 2022). "In the pathogenesis of RCC, a dysregulated metabolic pathway is involved, and genetic alterations such as loss of von Hippel Lindau (VHL) gene function were found in clear cell renal cell carcinoma (ccRCC), the most common type among renal cell carcinomas." (PMID 34679636, 2021). "Clear cell renal cell carcinoma (ccRCC) is the most frequent type of renal cell carcinoma (RCC) and is closely associated with mutations of the von Hippel-Lindau (VHL) gene." (PMID 34922551, 2021). "Moreover, both ROS generation and NOX4 expression are essential for HIF-2α transcriptional activity in VHL-deficient renal cell carcinoma, indicating that higher levels of ROS can contribute to HIF-2α stabilization and are key to facilitate and sustain the aggressive phenotype of cancer cells." (PMID 33540838, 2021). "In clear cell renal cell carcinoma (ccRCC), the most common histological variant of RCC, the Von Hippel-Lindau (VHL) tumor suppressor gene is silenced, which leads to activation of hypoxia inducible transcription factors, HIF-1α and HIF-2α." (PMID 34731180, 2021). "Loss of the tumor suppressor VHL is causally linked to renal cell carcinoma (RCC), and we and others have demonstrated the loss of primary cilia in VHL-deficient cells." (PMID 34002003, 2021). "Approximately 70% of RCC cases are clear cell renal cell carcinoma with von Hippel–Lindau (VHL) gene mutation and activation of the vascular endothelial growth factor (VEGF) pathway." (PMID 34319001, 2021). "Biallelic VHL inactivation in renal cell carcinoma (RCC) is indeed associated with increased HIF-1α, which is responsible for the highly vascular nature of RCC." (PMID 33467713, 2021). "STF-31 is a small molecule that was firstly reported to selectively target von Hippel-Lindau (VHL)-deficient renal cell carcinoma (RCC) cells." (PMID 31936350, 2020). "To study the distinct transcriptional responses provoked by HIF1α or HIF2α in renal cell carcinoma (RCC), we used WT8 cells that were generated by restoration of VHL expression into the 786-O VHL deficient RCC cell line." (PMID 33321829, 2020). "Several pieces of evidence have implicated this gene as a gatekeeper gene in the pathogenesis of RCC, these including VHL gene mutations in most primary sporadic renal cell carcinomas (RCCs) and the development of renal cysts in Vhl conditional knockout mice." (PMID 31980715, 2020). "Together, these data suggest that the highly proliferative, decreased-p400 subgroup of renal cell carcinomas represents tumors that are characterized by a loss of senescence, making senescence an efficient tumor-suppressive mechanism that must be overcome to develop VHL-associated neoplasia." (PMID 33167349, 2020). "Interestingly, in contrast to our findings that classify STF-62247 as an inducer of autophagic flux and ACD, STF-62247 has recently been reported to block late stages of autophagy by inducing lysosomal disruption in von Hippel-Lindau (VHL)-deficient renal cell carcinoma cells." (PMID 31959760, 2020).